STAT3 (signal transducer and activator of transcription 3)
Diseases named in the same sentence as STAT3 in open-access papers (continued):
Sharing a sentence is not in itself a finding about the gene and the disease.
liver cancer (continued). "HBV promotes the migration of liver cancer cells by downregulating miR-340-5p expression to induce STAT3 overexpression." (PMID 28413603, 2017). "We then defined a link between SMAD7 expression and STAT3 signaling in liver cancer by detecting increased pSTAT3 expression in liver tissue of SMAD7 KO mice." (PMID 28134936, 2017). "It is particularly worth mentioning that CD24 has been found to be a functional marker to regulate tumor initiation and self-renewal by signal transducer and activator of transcription 3 (STAT3)-mediated Nanog regulation in liver cancer." (PMID 27521216, 2016). "IL-6 has a key role in carcinogen-driven liver cancer development, promotes cancer cell proliferation, and inhibits the apoptosis of cancer cells through the activation of STAT3." (PMID 27589954, 2016). "The cellular mechanisms contributing to colorectal and liver cancer are not well understood but involve signaling protein dysregulation, including the persistent activation of STAT3." (PMID 26883202, 2016). "Our findings in this study provide novel evidence for an active role of Stat3 promotion of liver cancer stem cell growth." (PMID 27833137, 2016). "The signaling pathways between NF-κB and STAT3 cooperate to promote the development and progression of colon, gastric and liver cancers as a central signaling hubs in inflammation-mediated tumors." (PMID 27049829, 2016). "The expression of IL-6 was observed to be 2.4 fold upregulated at the protein level and that for Stat3 about 3.5 fold upregulated at transcript level in DEN-induced hepatic cancer as compared to control mice." (PMID 27760163, 2016). "High STAT3 activity levels, which depend on STAT3 phosphorylation, have been observed in primary liver cancer." (PMID 25360179, 2014). "Elevated STAT3 activity, which depends on phosphorylation, has been observed in primary liver cancer." (PMID 25360179, 2014). "Previous studies observed that STAT3 and NF-κB activation are mutually exclusive in liver cancer tissues, and the molecules are engaged in positive and negative crosstalk." (PMID 25360179, 2014). "While IL-6-dependent STAT3 activation is considered a key event in inflammation-induced liver cancer, the anti-inflammation effect of estrogen is well documented." (PMID 24708807, 2014). "In conclusion, the results suggested a tumorigenic role of PKR in liver cancer and a detailed mechanism involving an oncogenic transcription factor, STAT3, is described." (PMID 25360179, 2014). "In conclusion, the present study has demonstrated that AEG-1 plays a significant role in the proliferation and apoptosis of liver cancer HepG2 cells via downregulated IL-6 secretion and Stat3 activation." (PMID 24348829, 2014). "The pivotal role of JAK/STAT-3 pathway in inflammation-related liver cancer was confirmed by SOCS knocking out studies." (PMID 23533994, 2013). "Our study demonstrates that in vivo monocytes can promote liver cancer cell proliferation via IL-6/STAT3 signaling pathway." (PMID 22136659, 2011). "Constitutively activated IL-6/STAT3 signaling has been detected in a wide variety of human cancers including liver cancer and is considered an important factor for cancer initiation, development, and progression." (PMID 22136659, 2011). "Another important evidence for the role of STAT3 in liver cancer development is that constitutively activated STAT3 is detected in cancer stem cells from HCC and likely contributes to liver cancer stem cell proliferation and survival." (PMID 22136659, 2011). "Constitutive STAT3 signaling contributes to liver cancer progression by promoting angiogenesis, survival, metastasis, and growth of liver cancer cells." (PMID 20712901, 2010). "The constitutive activation of STAT3 in liver cancer is frequently due to the aberrant methylation and silencing of Suppressor of Cytokine signaling-1 (SOCS-1) and -3 (SOCS-3)." (PMID 20712901, 2010).
liver cancer (continued). "It has been shown that blockage of EGFR and STAT3 cascades resulted in the inhibition of cancer cell proliferation and growth of prostate and liver cancer via cell cycle arrest and apoptosis." (PMID 18302761, 2008). "Notably, the expression of SNHG16 is significantly elevated in liver cancer tissues and cell lines, where it exerts oncogenic effects through pathways such as miR-17-5p/p62, miR-4500/STAT3, and miR-605-3p/TRAF6/NF-κB." (PMID 40427707, 2025). "Upon external stimulation, STAT3 may form condensates via LLPS, activating genes associated with proliferation, angiogenesis, and immune evasion in liver cancer." (PMID 41280670, 2025). "Furthermore, antigens secreted by S. mansoni have been found to activate human and hamster liver cells by inducing c-Jun and STAT3, crucial regulators of liver cancer." (PMID 41387891, 2025). "STAT3 enhances the proliferation and invasion of liver cancer cells." (PMID 40698038, 2025). "It decreases STAT3 activation and boosts STAT3 protein degradation in hepatic cancer cells." (PMID 40219344, 2025). "For instance, high BMI boosts Interleukin-6 and tumor necrosis factor production, triggering hepatic inflammation and activating the oncogenic transcription factor STAT3 (signal transducer and activator of transcription 3), thereby driving liver cancer progression." (PMID 40717954, 2025). "Additionally, STAT3 modulates the expression of immune checkpoint molecules, enabling liver cancer cells to evade immune surveillance, thereby facilitating tumor progression." (PMID 41280670, 2025). "Besides, accumulating evidences have demonstrated that paeonol and forsythoside A, the effective components in JJJG, can act on the key pathological mechanism of (IL-6, TNF-α, IL-1β)/JAK2/STAT3/VEGF in the treatment of liver cancer and acute lung injury." (PMID 39494342, 2024). "Our study confirmed that nifuroxazide can effectively inhibit the expression of p-STAT3 and PD-L1 in liver cancer cells, which may be the reason for the increased apoptosis of these cells." (PMID 38441416, 2024). "This study uncovers the previously unknown role of HLJ1 in suppressing liver cancer with peritumoral STAT3 inhibition, and thus HLJ1 reinforcement could be a promising strategy for both liver cancer treatment and prevention." (PMID 39738726, 2024). "STAT3 is hyperactivated in different tumors, such as liver cancer." (PMID 38183094, 2024). "We investigated the effect of STAT3 decoy ODN on hepatic cancer cell proliferation." (PMID 38338338, 2024). "Hence, it is necessary to further study the relationship between JAK2/STAT3 pathway and inhibition of K73-03 on liver cancer cells." (PMID 38185661, 2024). "Therefore, the NF-κB and STAT3 pathways have already been used as targets in studies seeking new agents to prevent or treat liver cancer." (PMID 39409068, 2024). "STAT3 is known to be hyperactivated in various cancer types, such as liver cancer." (PMID 38183094, 2024). "Phosphorylated STAT3 is more aggressive against liver cancer." (PMID 38338338, 2024). "The expression of Stat3, which mediates several reciprocal interactions between liver cancer cells and stromal cells that modulate chronic inflammation and tumor formation, was significantly increased in the livers of hRipk3-KI and hMlkl-KI mice starting at 8 months of age." (PMID 39514172, 2024). "The development of liver cancer stem cells (LCSCs) and the preservation of their characteristics during the liver cancer process involve several signaling pathways, including Wnt/Catenin, Hippo, IL-6/STAT3, MAPK, and Notch pathways." (PMID 39494254, 2024). "Using cDNA microarray analysis, we demonstrated that HLJ1 deficiency alters hepatic gene signatures associated with chemical-induced liver cancer and IL-6/STAT3 signaling, and HLJ1 knockout mice showed pronounced STAT3 activation in normal liver adjacent to DEN-induced tumors." (PMID 39738726, 2024).
liver cancer (continued). "STAT3 decoy ODN inhibited hepatic cancer cell proliferation in a dose-dependent manner, and the inhibitory effect was significant at a concentration of 500 nM in HuH-7 cells and 1000 nM in HepG2 cells when compared to the maximum concentration of Lipofectamine (p < 0.01)." (PMID 38338338, 2024). "Simultaneously, 3-formylchromone inhibits the expression of Bcl-2, Bcl-xL, Survivin, and Mcl-1 in liver cancer cells, suggesting that 3-formylchromone promotes apoptosis in liver cancer cells by suppressing the STAT3 pathway and weakening CXCL12-driven metastasis." (PMID 38920657, 2024). "Additionally, it has been reported to increase STAT3 protein degradation in liver cancer cells while decreasing STAT3 activation." (PMID 36840034, 2023). "STAT3 has been shown to modulate cell survival and proliferation, whether alteration of liver cancer cell growth mediated STAT3 upregulation or downregulation is caused by both cell survival and proliferation remains unclear." (PMID 36656267, 2023). "To validate whether STAT3 promotes liver cancer cell growth in vivo, we injected HepG2 cells into nude mice and measured tumor sizes regularly during tumor formation." (PMID 36656267, 2023). "A combination of curcuma zedoary and kelp could inhibit liver cancer cell proliferation and metastasis by inhibiting endogenous H2S production and down-regulating the transcription activator 3 (STAT3)/BCL-2 and VEGF pathway in vitro and in vivo." (PMID 36865794, 2023). "A second report documented the inactivation of the JAK2/STAT3 pathway in a liver cancer model, in a similar fashion: a curcumin analog, GL63, contributes to a decreased expression of circZNF83, a sponge for miR-324-5p, whose target is cyclin-dependent kinase 16 (CDK16)." (PMID 37376060, 2023). "STAT5 in liver cancer seems to counteract the STAT3 signaling pathway." (PMID 37369132, 2023). "Furthermore, C. phaeocaulis can inhibit the growth of liver cancer cells by inhibiting STAT3 activity, and C. longa acts as a PARP inhibitor to induce apoptosis in cervical cancer cells and so on." (PMID 37746000, 2023). "NF-kb and STAT3 play an essential role in developing and regulating liver cancer." (PMID 38322013, 2023). "Moreover, constitutive activation of STAT3 modulates NF-κB signaling and enhances liver cancer stemness." (PMID 37642779, 2023). "The whole-cell vaccine for liver cancer targeting STAT3 reversed the depletion of T cells and NK cells in the liver cancer microenvironment, which may be attributed to the low expression of PD-1 and TIGIT." (PMID 35433470, 2022). "DILC has been found to modulate liver cancer stem cells through IL-6/STAT3 axis." (PMID 34991683, 2022). "These indicate that regulating IL-6/JAK2/STAT3 signaling pathway may be a therapeutic strategy for liver cancer." (PMID 36591515, 2022). "In addition, lnc-DILC modulates the crosstalk between TNF-α/ NF-κB signalling and IL-6/STAT3, resulting in a decreased hepatic inflammation and liver cancer stem cell proliferation." (PMID 36207500, 2022). "In addition, STAT3 signal regulates hepatic LD accumulation in diabetic mice and promotes the “Warburg effect” in liver cancer 46-48." (PMID 36451864, 2022). "Ni and colleagues found that miR-515-5p could suppress the migration and invasion of liver cancer cells through targeting IL6/JAK/STAT3 pathway." (PMID 36276992, 2022). "Importantly, Tex10 has been found to be elevated in liver cancer cells and liver cancer stem cells, as well as Tex10 overexpression facilitates cancer stem cell properties by activating STAT3 pathway." (PMID 35156514, 2022). "Additionally, our previous study showed that HBX was capable of promoting the levels of IL-34 to activate STAT3 and further facilitate the growth and migration of liver cancer cells." (PMID 35251017, 2022). "Moreover, HOAX11-AS was reported to promote the progression of liver cancer via the signaling pathway of miR-15a-3p/STAT3." (PMID 35700456, 2022).
liver cancer (continued). "Therefore, we did not observe any significant effect of STAT1 protein depletion on STAT3 protein activation or on STAT3 target gene expression in three different liver cancer cell lines." (PMID 35267462, 2022). "This study focused on the role of STAT1 and STAT3 signaling in liver cancer." (PMID 35267462, 2022). "Melvin and colleagues reported that STAT3 affects the progression of liver cancer." (PMID 36555586, 2022). "However, the interplay between STAT1 and STAT3 signaling in liver cancer cells and the immune cell composition regarding STAT1 and STAT3 expression in the tumor cells is still unclear." (PMID 35267462, 2022). "UA suppressed tumor growth and STAT3 phosphorylation in a HepG2 liver cancer xenograft mice model." (PMID 36296934, 2022). "Crocin inhibits the DNA-binding activity of STAT3 in IL-6-stimulated liver cancer cells." (PMID 34639131, 2021). "STAT3 is not only a key anti-inflammatory signal molecule in liver inflammation and fibrosis but also an important factor in promoting the occurrence of liver cancer." (PMID 34483930, 2021). "Momelotinib inhibits the phosphorylation of Jak2 and STAT3, and the inhibitory effect of this phosphorylation may affect the subsequent molecular signal transmission of liver cancer cells." (PMID 34199353, 2021). "In recent years, an increasing number of studies have revealed that the IL-6/STAT3 signaling pathway plays a pivotal role in the development of liver cancer, and many studies have shown that inhibition of the IL-6/STAT3 signaling pathway can block the occurrence and progress of HCC." (PMID 34976809, 2021). "Meanwhile, inhibitors of the IL-6/STAT3 signaling pathway should be promoted, and the efficacy and safety of these targeted inhibitors should be evaluated, it is need to formulate the standardization of clinical individualization treatment for liver cancer." (PMID 34976809, 2021). "Suppresses liver cancer stem cell expansion through inhibition of autocrine IL-6/STAT3 signaling." (PMID 33968749, 2021). "Importantly, activation of the CYP2C9 and STAT3 signaling pathway resulted in the sensitization of liver cancer stem cells to anticancer drugs, especially in advanced stages." (PMID 33380233, 2021). "Thereby, MVA signaling pathway, AMPK and STAT3 activities may represent potential therapeutic targets in liver cancer." (PMID 33718197, 2021). "Additionally, previous studies have revealed that lncRNA TSLNC8 and DILC regulate liver cancer development via STAT3 signaling." (PMID 34057016, 2021). "The roles of NF-κB and STAT3 in colon, gastric, and liver cancers have been extensively investigated and the activation and interaction between STAT3 and NF-κB plays a fundamental role in the control of the communication between cancer cells and inflammatory cells." (PMID 33917855, 2021). "Moreover, the ROS/STAT3 signaling axis has been reported to induce tumor progression in pancreatic, prostate and liver cancers." (PMID 34858425, 2021). "Additionally, AD was shown to be capable of activating PI3K/Akt1 and STAT3 in some cell types, such as the epithelial cells and the liver cancer cells." (PMID 33815378, 2021). "Long non-coding RNA DILC regulates liver cancer stem cells via IL-6/STAT3 axis." (PMID 33234142, 2020). "STAT3 regulates the upregulation of lncRNA to affect in liver cancer metastasis." (PMID 32280300, 2020). "In addition, IL-6 derived from CAFs can activate STAT3 in DCs, which subsequently induce liver cancer immune escape through impairing T-cell proliferation and promoting Treg cells expansion." (PMID 32972405, 2020). "XCHD inhibits the growth of liver cancer cells via the JAK2/STAT3 pathway." (PMID 33029173, 2020). "Similarly, the suppression of STAT3 signaling by honokiol inhibited liver cancer cell proliferation and potentiated the apoptotic effects of paclitaxel and doxorubicin." (PMID 32252311, 2020).
liver cancer (continued). "These different results regarding the correlation between TLR4 expression and STAT3 activation in liver cancer may be because of the different sample sizes of the two analyses." (PMID 32312954, 2020). "Tumor cell-intrinsic Tim-3 promotes liver cancer via NF-κB/IL-6/STAT3 axis." (PMID 33234142, 2020). "For example, miR-298 binds to the STAT3 mRNA 3′UTR to regulate the growth of liver cancer cells." (PMID 32104542, 2020). "In addition, we also found that increased STAT3 in liver cancer cells also regulates circSOD2 expression in a feedback way." (PMID 33234142, 2020). "Our findings provide two pieces of new information that may increase our understanding why STAT3 is transcriptionally activated in liver cancer." (PMID 31547152, 2019). "In addition, STAT3/NF-κB1 signaling plays an important role the development and progression of colon, gastric, and liver cancers, as well as the control of immune responses." (PMID 29874806, 2018). "In addition, the IL6/JAK2/STAT3 signalling pathway was demonstrated to be involved in CD90+ liver cancer stem cell function modulation in our assays." (PMID 29722127, 2018). "Taken together, these data showed that CK induced ERS and apoptosis by inhibiting p-STAT3 in human liver cancer cells; thus, CK might be a potential therapeutic candidate for human HCC." (PMID 29921768, 2018). "So, in this study, we further investigated whether Raloxifene has the ability to inhibit IL-6/GP130/ STAT3 signaling and suppress tumor growth in liver cancer cells." (PMID 28430601, 2017). "Our results suggest that Raloxifene is a potent IL-6/GP130 inhibitor and may be a chemoprevention agent for liver cancer by targeting persistent STAT3 signaling." (PMID 28430601, 2017). "Although, FRK-VK and VF mutants were shown to increase STAT3 phosphorylation in liver cancer." (PMID 29348886, 2017). "Here we clarified that CT could enhance the efficacy of ATO in treating liver cancer and that phosphorylated-STAT3 may play a key role." (PMID 28187727, 2017). "Our findings, showing that increased STAT3 expression, resulting from downregulation of the migration inhibitor miR-340-5p, thus provide a theoretical basis for the development of novel clinical treatments of HBV-associated liver cancer." (PMID 28413603, 2017). "So we detected the effect of Raloxifene on STAT3 translocation in Hep-3B liver cancer cells." (PMID 28430601, 2017). "Here we try to elucidate how CT could enhance the efficacy of ATO for treating liver cancer and its correlation to STAT3 in vitro and in vivo." (PMID 28187727, 2017). "Raloxifene is a suitable agent for targeting liver cancer and possibly certain type of cancer cells with constitutively activated STAT3 induced by IL-6, due to its ability to inhibit IL-6/GP130 binding as well as their potent growth suppressive activity both in vitro and in vivo." (PMID 28430601, 2017). "The possible effect of Raloxifene in STAT3 signaling or liver cancer cells is still unclear." (PMID 28430601, 2017). "STAT3 has been found to contribute to oncogenesis including liver cancer." (PMID 28430601, 2017). "To confirm whether Raloxifene has the potential of growth-suppressive in liver cancer, we first examined the effect of Raloxifene on constitutive STAT3 phosphorylation induced by IL-6 in Hep-3B liver cancer cells." (PMID 28430601, 2017). "In addition, sorafenib, a first-line therapy in treating patients with advanced liver cancer, demonstrats anti-tumor activity through the inhibition of STAT3 signaling." (PMID 26061710, 2017). "To examine whether ATO combined with CT–induced liver cancer cell apoptosis was related to the JAK/STAT3 signaling pathway, we detected the expressions of phosphorylated-JAK2 and phosphorylated-STAT3-Tyr705." (PMID 28187727, 2017). "However, few inhibitors targeting up-streams of STAT3 are available for the therapy of liver cancer." (PMID 28430601, 2017). "Persistent activation of STAT3 signaling is frequently detected in colon and liver cancers." (PMID 26883202, 2016).